TMEM201 (transmembrane protein 201)
Description:
Critical regulator of angiogenesis and endothelial cell (EC) migration. Promotes the migration of endothelial cells, which is essential for angiogenesis. Interacts with the linker of nucleoskeleton and cytoskeleton (LINC) complex, which plays a vital role in connecting the cell's cytoskeleton to the nuclear envelope. This interaction is essential for maintaining cellular structure and facilitating the movement of endothelial cells, which is critical for proper vascular development. Involved in nuclear movement during fibroblast polarization and migration (By similarity). Overexpression can recruit Ran GTPase to the nuclear periphery. [Isoform 2]: May define a distinct membrane domain in the vicinity of the mitotic spindle. Involved in the organization of the nuclear envelope implicating EMD, SUN1 and A-type lamina.
Synonyms: NET5; SAMP1; RP13-15M17.2; Ima1
Tractability: Antibody: UniProt predicts a signal peptide or a membrane-spanning region. PROTAC: ubiquitination databases record sites on it; its protein half-life has been measured.
Gene: Protein-coding gene on chromosome 1 (9,588,721 to 9,614,877, forward strand). Ensembl gene ENSG00000188807.
Subcellular location: Nucleus inner membrane; Nucleus inner membrane (Isoform 2); Cytoplasm, cytoskeleton, spindle pole
Subcellular location (Human Protein Atlas): Nuclear membrane; Nucleoplasm
Gene Ontology:
Molecular function: protein binding; actin filament binding; lamin binding
Biological process: angiogenesis; positive regulation of endothelial cell migration; nuclear migration along microtubule
Cellular component: nuclear inner membrane; nuclear membrane; nucleoplasm; spindle pole
Genetic constraint (gnomAD): Loss-of-function variants: 25 observed, 56.63 expected, observed/expected ratio (o/e) 0.44, 90% interval 0.32 to 0.62. The upper end of that interval is the gene's LOEUF score, 0.62, which puts it in group 2 of 6, group 1 being the genes least tolerant of losing a copy. Missense variants: 771 observed, 889.05 expected, observed/expected ratio (o/e) 0.87, 90% interval 0.82 to 0.92. Synonymous variants: 403 observed, 411.44 expected, observed/expected ratio (o/e) 0.98, 90% interval 0.9 to 1.06.
Homologues: Orthologues: chimpanzee TMEM201 (100% identical), macaque TMEM201 (97% identical), dog TMEM201 (88% identical), pig TMEM201 (88% identical), rabbit TMEM201 (86% identical), mouse Tmem201 (83% identical), rat Tmem201 (83% identical), guinea pig TMEM201 (82% identical).
Diseases named in the same sentence as TMEM201 in open-access papers:
TMEM201 is named in the same sentence as 39 diseases in open-access papers, as found by Europe PMC text mining. Sharing a sentence is not in itself a finding about the gene and the disease. The quoted sentences say what the papers report.
muscular dystrophy (2 papers, 2018 to 2022). Muscular dystrophy (MD) refers to a group of more than 30 genetic diseases characterized by progressive weakness and degeneration of the skeletal muscles that control movement. "Intriguingly, mutations in PLPP7, TMEM38A, and TMEM201 have been identified in muscular dystrophy patients with an EDMD-like phenotype, which highlights the importance of these proteins in muscle disease." (PMID 36699009, 2022).
congenital muscular dystrophy (1 paper, 2020). A muscular dystrophy that is characterized by diminished muscle tone (hypotonia), progressive muscle weakness and degeneration (atrophy), abnormally fixed joints, spinal rigidity, and delays in reaching motor milestones such as sitting or standing unassisted. "The patient with the combined LMNA and TMEM201 mutations had a very early age of onset (1 year), suggesting that both mutations contribute to the more severe (congenital) phenotype as the LMNA mutation has not been associated with congenital muscular dystrophy." (PMID 31862442, 2020).
fungal infection (1 paper, 2014). "For example, dps-miR-210b was downregulated by fungal infection, and targeted mRNAs encoding RNA-binding motif protein 8a, transmembrane protein 201, 1-acylglycerol-3-phosphate acyltransferase and quiescin sulfhydryl oxidase." (PMID 25149864, 2014).
hepatoma (1 paper, 2023). "The potential of si-TMEM201 to inhibit hepatocarcinogenesis was subsequently validated in the hepatoma cell lines." (PMID 37373430, 2023). "In addition, the function of TMEM201, a feature of the TMEMs signature, was verified for the first time in hepatoma cells." (PMID 37373430, 2023). "The RT–qPCR analysis validated the expressed TMEM201 level in the hepatoma cell lines." (PMID 37373430, 2023). "Furthermore, both cohorts demonstrated a significant relationship between the high expression of TMEM201 and the increased expression of MICA, which was confirmed in the si-TMEM201 hepatoma cell lines." (PMID 37373430, 2023).
cancer (3 papers, 2017 to 2023). A tumor composed of atypical neoplastic, often pleomorphic cells that invade other tissues. "The si-TMEM201 HCC cell lines expressed TMEM201 at a lower level compared to the NC group, demonstrating the cancer-promoting properties of TMEM201." (PMID 37373430, 2023).
tumor (2 papers, 2013 to 2023). "Moreover, high TMEM201 levels were significantly correlated with increased MICA expression, which plays a role in tumor-immune-escape mechanisms." (PMID 37373430, 2023).
TMEM201 also shares sentences with these, for which no sentence is quoted: ileitis (28 papers); colitis (12); Crohn disease (12); fibrosis (3); inflammatory bowel disease (3); alopecia (2); enteropathy (2); glomerulosclerosis (2); inflammation (2); iron deficiency (2); periodontitis (2); renal fibrosis (2); abscess (1); adenoma (1); amyloidosis (1); Arthritis (1); breast carcinoma (1); cardiomyopathy (1); chronic kidney disease (1); Emery-Dreifuss muscular dystrophy (1); enteritis (1); Hearing impairment (1); Immunodeficiency (1); infection (1); intestinal disease (1); intestinal inflammation (1); Lewis lung carcinoma (1); non-alcoholic steatohepatitis (1); of ileum (1); presbycusis (1).
A further 3 diseases each share a sentence with TMEM201 in 1 paper.